GNL2 (G protein nucleolar 2)
Description:
GTPase that associates with pre-60S ribosomal subunits in the nucleolus and is required for their nuclear export and maturation.
Synonyms: NGP1; Ngp-1; HUMAUANTIG; Nog2; Nug2
Tractability: Small molecule: a structure with a bound ligand is known. PROTAC: ubiquitination databases record sites on it; its protein half-life has been measured.
Gene: Protein-coding gene on chromosome 1 (37,566,815 to 37,595,955, reverse strand). Ensembl gene ENSG00000134697.
Subcellular location: Nucleus, nucleolus
Subcellular location (Human Protein Atlas): Nucleoli; Nucleoli rim
Gene Ontology:
Molecular function: RNA binding; GTP binding; GTPase activity
Cellular component: membrane; nucleolus; nucleus
Genetic constraint (gnomAD): Loss-of-function variants: 24 observed, 41.58 expected, observed/expected ratio (o/e) 0.58, 90% interval 0.42 to 0.81. The upper end of that interval is the gene's LOEUF score, 0.81, which puts it in group 3 of 6, group 1 being the genes least tolerant of losing a copy. Missense variants: 484 observed, 557.36 expected, observed/expected ratio (o/e) 0.87, 90% interval 0.81 to 0.94. Synonymous variants: 177 observed, 197.27 expected, observed/expected ratio (o/e) 0.9, 90% interval 0.79 to 1.02.
Homologues: Orthologues: chimpanzee GNL2 (99% identical), macaque GNL2 (98% identical), pig GNL2 (89% identical), dog GNL2 (88% identical), mouse Gnl2 (86% identical), rabbit GNL2 (86% identical), guinea pig GNL2 (85% identical), rat Gnl2 (85% identical), tropical clawed frog gnl2 (71% identical), zebrafish gnl2 (67% identical), Drosophila melanogaster Ns2 (46% identical), Caenorhabditis elegans ngp-1 (41% identical). Paralogues in human: GNL3L (19% identical), GNL3 (19% identical), LSG1 (15% identical), GNL1 (15% identical), NOA1 (12% identical), MTG1 (11% identical).
Diseases named in the same sentence as GNL2 in open-access papers:
GNL2 is named in the same sentence as 12 diseases in open-access papers, as found by Europe PMC text mining. Sharing a sentence is not in itself a finding about the gene and the disease. The quoted sentences say what the papers report.
ovarian carcinoma (2 papers, 2015 to 2023). A malignant neoplasm originating from the surface ovarian epithelium. "Increased expression of GNL2 was correlated with poor prognosis in ovarian cancer patients with 1p34.3 amplifications." (PMID 38110868, 2023).
glioma (1 paper, 2025). A benign or malignant brain and spinal cord tumor that arises from glial cells (astrocytes, oligodendrocytes, ependymal cells). "Knockdown of GNL2 reduced glioma cell migration and invasion." (PMID 39949372, 2025). "GNL2 enhances the synthesis of ribosomal protein L11 (RPL11), thereby promoting glioma development." (PMID 39949372, 2025).
liver carcinoma (1 paper, 2021). An epithelial or non-epithelial malignant neoplasm that arises from the liver. "We conducted KEGG and GO enrichment analyses of genes coexpressed with GNL2 in LIHC tumor and normal tissues to validate the function of GNL2 in liver carcinoma." (PMID 34337013, 2021).
periodontitis (1 paper, 2023). An acute or chronic inflammatory process that affects the tissues that surround and support the teeth. "Results from another scRNA-seq data of periodontitis revealed GNL2 was upregulated in T cells." (PMID 38110868, 2023).
polycystic kidney disease (1 paper, 2022). A usually autosomal dominant and less frequently autosomal recessive genetic disorder characterized by the presence of numerous cysts in the kidneys leading to end-stage renal failure. "Gene-based analysis also highlighted several other genes, including a gene implicated in polycystic kidney disease (TMEM207), a gene expressed at the tight junction of renal tubule epithelial cells (CLDN1), and a gene associated with cell proliferation (GNL2)." (PMID 36275661, 2022).
cancer (6 papers, 2015 to 2025). A tumor composed of atypical neoplastic, often pleomorphic cells that invade other tissues. "In our study, we found that GNL2 was largely associated with altered ribosome biogenesis in cancer cells through KEGG and GO enrichment analyses, thereby playing a vital role in carcinoma initiation and progression." (PMID 34337013, 2021). "After analysis of the associations between various pathological carcinoma stages of LIHC patients and GNL2 expression, the data revealed that high expression of GNL2 was significantly associated with advanced cancer stages." (PMID 34337013, 2021). "It was found that GNL2 expression was significantly associated with the pathological carcinoma stages of LIHC (P = 0.00163)." (PMID 34337013, 2021). "Given GNL2’s role in promoting the G1 to S phase transition and its overexpression in various cancers, this downregulation strongly implies a cell cycle arrest before the G2-M transition." (PMID 40429796, 2025). "Enrichment analysis suggested that GNL2 was largely related to ribosome biosynthesis which was essential for cancer unrestricted growth." (PMID 34337013, 2021). "Lots of targets were the same between the two cancer types, like GNL2 at 1p34.3, PVT1 at 8q24, and HOXB genes at 17q21.32, indicating some common genetics shared between these two gynecologic tumors." (PMID 33815481, 2021). "Then, GEPIA analysis discovered the associations between various pathological carcinoma stages of LIHC patients and GNL2 expression level." (PMID 34337013, 2021). "After enrichment analysis, the data revealed that the genes coexpressed with GNL2 probably participated in ribosome biosynthesis which was essential for unrestricted growth of carcinoma." (PMID 34337013, 2021). "Bioinformatics analysis showed that GNL2 was greatly raised in LIHC, and its overexpression was closely related to cancer stage and poor prognosis." (PMID 34337013, 2021). "After analysis of gene expression profile from The Cancer Genome Atlas (TCGA) database, GNL2 was largely heightened in LIHC, and its overexpression displayed a close relationship with different stages and poor prognosis of carcinoma." (PMID 34337013, 2021). "Presently, there are no researches on the particular biological function of GNL2, and little is known about its relationship with carcinoma pathogenesis." (PMID 34337013, 2021). "The increased expression of hub genes GNL2, RPS23, and IMP4 was not significant in GEPIA, but other studies have reported the increased expression of GNL2, RPS23, and IMP4 in cancer." (PMID 39949372, 2025).
tumor (2 papers, 2021). "As far as gene expression information from the TCGA database, GNL2 was highly expressed in LIHC tumor samples compared to that in normal samples, implying GNL2 was a possible oncogene in LIHC." (PMID 34337013, 2021). "TCGA database analysis showed that LIHC tumor tissues highly expressed GNL2 in comparison with normal tissues." (PMID 34337013, 2021). "GNL2, an RNA-binding protein, is lack of reports in tumor and has been reported to be involved in the biological development." (PMID 34235075, 2021).
GNL2 also shares sentences with these, for which no sentence is quoted: breast carcinoma (1 paper); gynecologic tumors (1); heart failure (1); kidney (1); lung carcinoma (1).